PRR16 (proline rich 16)
Description:
Regulator of cell size that promotes cell size increase independently of mTOR and Hippo signaling pathways. Acts by stimulating the translation of specific mRNAs, including those encoding proteins affecting mitochondrial functions. Increases mitochondrial mass and respiration.
Synonyms: DSC54; LARGEN
Tractability: PROTAC: ubiquitination databases record sites on it.
Gene: Protein-coding gene on chromosome 5 (120,464,300 to 120,687,332, forward strand). Ensembl gene ENSG00000184838.
Subcellular location (Human Protein Atlas): Nucleoplasm; Cytosol; Midbody
Gene Ontology:
Molecular function: protein binding
Biological process: positive regulation of cell size; positive regulation of translation
Genetic constraint (gnomAD): Loss-of-function variants: 5 observed, 16.9 expected, observed/expected ratio (o/e) 0.3, 90% interval 0.15 to 0.62. The upper end of that interval is the gene's LOEUF score, 0.62, which puts it in group 2 of 6, group 1 being the genes least tolerant of losing a copy. Missense variants: 403 observed, 367.95 expected, observed/expected ratio (o/e) 1.1, 90% interval 1.01 to 1.19. Synonymous variants: 143 observed, 143.04 expected, observed/expected ratio (o/e) 1, 90% interval 0.87 to 1.15.
Homologues: Orthologues: chimpanzee PRR16 (100% identical), macaque PRR16 (98% identical), pig PRR16 (93% identical), mouse Prr16 (93% identical), rat AABR07032097.1 (92% identical), rabbit PRR16 (90% identical), dog PRR16 (79% identical), tropical clawed frog prr16 (72% identical), guinea pig PRR16 (59% identical), zebrafish prr16 (42% identical). Paralogues in human: INSYN1 (27% identical).
Diseases named in the same sentence as PRR16 in open-access papers:
PRR16 is named in the same sentence as 5 diseases in open-access papers, as found by Europe PMC text mining. Sharing a sentence is not in itself a finding about the gene and the disease. The quoted sentences say what the papers report.
asthma (1 paper, 2025). "For asthma and COPD, one SNP rs11168048 located at 5q32 (harboring HTR4, FBXO38, and SPINK7) and two SNPs rs2122190 located at 5q23.1 (harboring PRR16) and rs6860087 located at 5q32 (harboring HTR4) were identified." (PMID 41295252, 2025).
leukemia (1 paper, 2021). A malignant (clonal) hematologic disorder, involving hematopoietic stem cells and characterized by the presence of primitive or atypical myeloid or lymphoid cells in the bone marrow and the blood. "Among the metabolic genes downregulated in NPM1/cohesin-mut compared with NPM1-mut AML, CHST13, ADCY9, PRR16, LPL, and SLC1A3 were confirmed by STAG2-deficient model of NPM1-mut leukemia." (PMID 34193978, 2021).
cardiovascular diseases (1 paper, 2022). "We identified two loci at 5q35 (ADAMTS2) and 5q23 (PRR16), not previously reported for T2D using CC-GWAS and Fam-meta; both genes play a role in cardiovascular diseases." (PMID 36182916, 2022).
PRR16 also shares sentences with these, for which no sentence is quoted: bladder cancer (1 paper); tumor (1).